FOXP3 (forkhead box P3)
Diseases named in the same sentence as FOXP3 in open-access papers (continued):
Sharing a sentence is not in itself a finding about the gene and the disease.
tumor (continued). "TIICs in the tumor microenvironment are assessed and quantified by categorizing immune cells into three subtypes: CD66b+ tumor-associated neutrophils (TANs), FoxP3+ regulatory T cells (Tregs), and CD163+ tumor-associated macrophages (TAMs)." (PMID 38730579, 2024). "Mutations in the FKH structural domain of Foxp3 has been found at the transcriptional level in HCC tumor tissues, affecting the function of controlling the expression of target genes." (PMID 38919615, 2024). "In BC lymphocyte recruitment, CCL17/CCL22 acts as a ligand for CCR4, and CCL17/CCL22 is closely associated with Foxp3+ tumor-infiltrating regulatory T cells (Ti-Tregs)." (PMID 39329710, 2024). "Alternatively, Foxp3 expression in CD8+ T cells has more recently been linked with metabolic reprogramming in the tumour microenvironment to promote sustained survival under restricted glucose availability, but with no suppressive capabilities." (PMID 39101538, 2024). "Analyses of Tregs in the HBV-associated HCC tumor microenvironment showed a more immunosuppressive and effective status, with increased expression levels of FOXP3, PD-1, CTLA-4, ICOS, and LAG-3 compared with non-HBV HCC." (PMID 38793588, 2024). "Foxp3 Tregs infiltrate tumors, suppress beneficial anti-tumor immunity, and are associated with poor prognosis." (PMID 39272810, 2024). "Recent reports demonstrated that FOXP3+ tumor-infiltrating lymphocytes (TILs) were associated with improved overall survival (OS) in HNSCC patients (HR: 0.80; 95% CI: 0.70–0.92)." (PMID 38474377, 2024). "IRPS is linked to an immunosuppressive tumor microenvironment characterized by activating forkhead box P3 (FOXP3+) CD4+ T lymphocytes, which further suppress T-cell functions and promote T-cell exhaustion." (PMID 39593745, 2024). "Elevated levels of FOXP3 in multiple tumor types has been reported to be associated with worse overall survival." (PMID 38806474, 2024). "At the invasive margin, high expression of CD3, CD4, CD8, and CD45RO, along with CD4 and FOXP3, at the tumor center was associated with improved overall survival." (PMID 38787209, 2024). "Abundant evidence suggests that an increased presence of endogenous FOXP3+ CD25+ CD4+ Treg cells in tumor tissues is associated with poor prognosis." (PMID 39668835, 2024). "Diets with increased saturated lipids promote tumor growth, increasing infiltration of CD206+ and PD-L1+ tumor-associated macrophages and FOXP3+ regulatory T cells." (PMID 39518123, 2024). "FoxP3+ Treg cells specialize in immune suppressive responses and are found to be highly infiltrated in the tumor microenvironment associated with poor prognosis." (PMID 36672677, 2023). "In general, we were able to observe that the high levels of FoxP3 were often associated with poor tumor staging for patients with ccRCC." (PMID 37569676, 2023). "In terms of this, STAT3 and Foxp3 interaction site was exist in the promoter of tumor induced Tregs and associated with several tumors progression." (PMID 36226375, 2023). "CD4+ regulatory T cells (Tregs) expressing the transcription factor FoxP3 promote tumor progression by effectively suppressing anti-tumor immunity, and scRNA-Seq identified many genes associated with Tregs." (PMID 36769267, 2023). "In line with previous study, we observed that Tregs probe genes expression in tumor was significantly different from non‐tumor, which was also associated with patient poor prognosis, especially Foxp3 and MMP12." (PMID 36226375, 2023). "The higher levels of FOXP3 Treg cells are associated with poor prognosis, indicating that FOXP3 Treg cells inhibit tumor immune surveillance and so promote tumor development and progression." (PMID 36672682, 2023). "Immunosuppressive cells, such as Foxp3 positive T regulatory cells, myeloid-derived suppressor cells, tumor associated macrophages, and cancer-associated fibroblasts are generally associated with negative prognostic values." (PMID 36891293, 2023).
tumor (continued). "In resected NSCLC, tumor‐infiltrating Foxp3+ regulatory T cells were associated with disease recurrence." (PMID 36621836, 2023). "FOXP3 lymphocytes indicate a CRC prognosis, but in other cancers the presence of high FOXP3 lymphocytes in the tumor microenvironment is associated with unfavorable prognoses." (PMID 37960147, 2023). "We also examined the association between the expression of cGAS-STING in tumor cells and the infiltrations of Treg cells (Foxp3+ cells) in pMMR CRC by IHC." (PMID 37345163, 2023). "In human cancers, TIM-3 is highly expressed in terminally exhausted CD8+ CTLs, Foxp3+ Tregs, tumor-associated macrophages, and MDSCs." (PMID 37928556, 2023). "In contrast, for the APCmin/+ model, the tumour infiltration of FOXP3+ T cells were reduced by myeloid-ILK deficiency whereas the infiltration of CD8+ T cells remained unaffected." (PMID 38077324, 2023). "In both models, the ratio of CD8+/FOXP3+ T cells in tumours were significantly elevated in myeloid-ILK deficient mice compared the ILK-sufficient controls." (PMID 38077324, 2023). "A direct association of VD t1 with CD4+ and FOXP3+ TILs in the invading tumor front was noted (p = 0.05 and 0.01)." (PMID 36900270, 2023). "The investigators found that PD-L1 positivity of the tumor was significantly associated with invasion of the stroma, which was accompanied by an increase in TAMs and FOXP3+ regulatory T lymphocytes." (PMID 38022518, 2023). "Evidences showed that Tregs are associated with tumour prognosis and that high expression of Foxp3 in tumour-infiltrating lymphocytes has been linked to a poor prognosis and a high risk of recurrence." (PMID 38259489, 2023). "High CD73 expression was associated with a higher ratio of Foxp3 + /CD8 + tumor-infiltrating lymphocytes (TILs) and CD163 + /CD68 + tumor-associated macrophages (TAMs)." (PMID 36899373, 2023). "Conversely, Th2 cells, Th17 cells, and Foxp3+ regulatory T (Treg) cells are commonly associated with tumor progression and poor prognosis." (PMID 37737709, 2023). "The major cellular players mediating GBM immunosuppression are CD4+ CD25+ Foxp3+ T regulatory cells (Tregs), myeloid-derived suppressor cells (MDSCs), and M2 polarized tumor-associated macrophages (TAMs)." (PMID 37114043, 2023). "Although there was no significant statistical difference in multivariate analysis, higher Foxp3+ Tregs signature was observed to be associated with worse EC patient's clinical outcomes, such as metastasis, pathological and tumor grade development." (PMID 36226375, 2023). "We found both PD-1+ and FOXP3+ lymphocytic infiltration to be associated with increased Ki67 expression, which is a tumor proliferative activity marker and a prognostic indicator in a number of solid malignancies." (PMID 37621817, 2023). "Firstly, STAT3/Foxp3 axis was associated with tumor progress in EC and enhanced Tregs infiltration, as well as the potential treatment option for Tregs inhibition." (PMID 36226375, 2023). "FOXP3 in tumor-infiltrating CD4+ T cells is generally associated with an intrinsic capacity to suppress tumor immunity." (PMID 37868998, 2023). "Compared with non-responders, patients with a partial response showed a significantly lower risk of relapse when their residual tumor exhibited high FOXP3, CD68, CD83, CD31 and CD34 content and IL15 expression but a low CD138 concentration." (PMID 37511057, 2023). "We detected a correlated increase in numbers of macrophages and Foxp3+ Treg cells in Ikka∆LU;KrasG12D ADCs that were associated with increased tumor burdens and reduced CD8 cell numbers compared to KrasG12D ADCs." (PMID 37686574, 2023). "It is generally believed that high CD8+ T-cells are associated with better prognosis and that tumor-associated macrophages (TAMs) and regulatory T-cells (FOXP3+) are associated with worse survival in uterine cancer, but study conclusions vary." (PMID 36672477, 2023).
tumor (continued). "Such LN-draining primary tumors, modified by tumor factors, lead to the formation of a metastatic niche associated with an increased number of Foxp3+ regulatory T cells (Tregs)." (PMID 38067325, 2023). "Infiltration of neoantigen-specific Th1 CD4+ T cells within the tumor was associated with a significant reduction in FOXP3+ Tregs." (PMID 38063199, 2023). "Conversely, regulatory T cells (Tregs), a subtype of CD4+ T cells characterized by the expression of CD25 and forkhead box P3 (FoxP3), are capable of suppressing the tumor immune response and are associated with the metastasis and recurrence of HCC." (PMID 37275909, 2023). "Regulatory T cells (Treg) are CD4+CD25+Forkhead box P3 (FoxP3)+ lymphocytes that maintain self-tolerance and immune homeostasis, and are known to infiltrate the tumor microenvironment (TME) and suppress cancer-associated inflammation." (PMID 37232845, 2023). "Tumoural PD-L1 expression was associated with a denser intratumoural regulatory T cell infiltrated as evidenced by higher CD4+/FOXP3+ cell density (40.8 vs. 12.3 cells/mm2, p = 0.001)." (PMID 37274775, 2023). "Accordingly, to examine the effect of myeloid-ILK deficiency on the tumour-infiltration of T cells, the tumour-infiltrated regulatory FOXP3+ and cytotoxic CD8+ T cells in both models of CRC were quantified." (PMID 38077324, 2023). "Infiltration of a large number of Treg cells into tumor tissues is often associated with poor prognosis, which was concordant with our result that infiltrations of FOXP3+ cells were associated with good prognosis in BTC." (PMID 36650632, 2023). "The presence of FOXP3+ Tumor-Infiltrating Lymphocytes (TILs) has been associated with the tumor’s expression of IL-33, and intriguingly, the prognostic value of FOXP3 appears to be contingent upon the active expression of IL-33." (PMID 37762328, 2023). "Exhaustion markers (PD-1, TIM3, CD39, and FOXP3) and their relationship with tumour-associated macrophages (CD163) were assessed by immunofluorescence on paraffin-embedded samples from n = 43 OE and n = 54 EAOC patients." (PMID 37569458, 2023). "Results obtained from the analyses showed that tumor samples express three variants with a differential frequency, FOXP3Δ2 with a frequency of 74%, FOXP3Δ7 with 17%, and FOXP3 X1 with 9%." (PMID 36672296, 2023). "One study demonstrated that tumor abundance of F. nucleatum was associated inversely with FOXP3+ cell infiltrates in colorectal cancer." (PMID 37538192, 2023). "Poor tumor grade is reportedly associated with increased FOXP3+ TILs and decreased CD8+ TILs in PDAC." (PMID 37477731, 2023). "A high proportion of CD8+ cells at the TM was associated with OS (p = 0.029), while in contrast to the tumour core a high proportion of FoxP3+ cells at the TM was associated with impaired survival (p = 0.069)." (PMID 37965317, 2023). "Tumor-associated Tregs highly express immunosuppressive molecules, including FOXP3, CTLA-4, PD-1, CD39, ICOS, CD38, and IL32, as well as several specific surface signaling molecules (PD-L1, PD-L2, interleukin-1 receptor 2, and chemokine CCR8)." (PMID 37187731, 2023). "CD4+ T cells isolated from tumor tissue downregulate granzymes B and H and upregulate genes associated with regulatory T cells (FOXP3, IKZF4, CD38, ISG15)." (PMID 37648263, 2023). "Penetration of the spatially connected Foxp3 + Tregs and CAFs in the tumor stroma is strongly associated with poor prognosis." (PMID 37723510, 2023). "Blocking PD1/PD-L1will not only promote anti-tumor immunity but also inhibit Treg cells and Forkhead Box P3 (FOXP3) expression, leading to loss of self-tolerance." (PMID 36911712, 2023). "Elevated levels of CD8+, CD8+ /CD4+, and FOXP3+ (major transcription factors of the regulatory T cell lineage) in preoperative tumor-infiltrating T lymphocytes were found to be associated with negative lymph nodes, early disease, and radical hysterectomy." (PMID 37729271, 2023).
tumor (continued). "FOXP3+ TILs infiltration and FOXP3+/CD8+ ratios were higher in inner tumor areas, linked with LDH5 expression, and higher MIB1 proliferation index (p = 0.03) and SMA expression (p = 0.001)." (PMID 36900270, 2023). "Accordingly, IGF1R deficiency decreased expression of p-IGF1R in blood vessels, fibroblasts, tumor-associated macrophages and FOXP3+ tumor-infiltrating lymphocytes." (PMID 35688943, 2022). "Certain studies have shown that tumor-infiltrating FoxP3+ Tregs are associated with a better prognosis in CRC patients." (PMID 35455287, 2022). "Th cells range from those that can dampen the immune response (such as Foxp3+ Treg), to those that can cause tumor destruction (such as IFN-γ-secreting Th1)." (PMID 35606804, 2022). "Our data support this finding, indicating that reduced FoxP3+ Tregs associated with a reduction in PD-L1 expression by myeloid cells in tumor-bearing mice administered a BRB-E-supplemented diet." (PMID 36016924, 2022). "Based on the TGF-β activity, the differentiation of Tregs (CD25+Foxp3+) impact the response of T cells and the neutralization of their activities is strongly implicated with the anti-tumor immune response." (PMID 36172343, 2022). "While the T-cell subsets associated with GC occurrence and progression are mainly tumor infiltrative forkhead box P3-positive (FOXP3+) Tregs, FOXP3 is a transcription factor that is specifically expressed by natural Tregs." (PMID 36225938, 2022). "Next, we analyzed the effect of Asm deficiency on the Foxp3+ Treg subpopulation in vitro, since we observed elevated frequencies of Tregs in dLN and tumors of tumor-bearing Asm-deficient mice." (PMID 36426850, 2022). "Again, all this applies to our “inflamed” subtype: FoxP3+ T cell densities were significantly higher than in “immune-desert/type A-like” tumours and they were positively associated with survival." (PMID 35140715, 2022). "Numerous clinical studies have demonstrated that antiangiogenic therapy, blocking VEGFR, used in human cancers is associated with a reduction of tumour-infiltrating FOXP3+ Treg cells." (PMID 36569832, 2022). "In the 4-nitroquinoline 1-oxide (4-NQO) carcinogen model of HNSCC, transiently knocking out FOXP3 cells in mice that express FOXP3 under a human diphtheria receptor caused increased T cell infiltrate in the tumor but 2.5 times increase in progression to HNSCC." (PMID 35937775, 2022). "Tumor immunophenotyping 1 week after treatment indicated loss of Foxp3+ regulatory T (Treg) cells in response to CTLA4 across genotypes." (PMID 36344707, 2022). "Defining the causes of quantitative differences in induced FoxP3+ Tregs and immune responses in the tumor microenvironment is a challenge for the future." (PMID 34319010, 2022). "The number of intratumoral Treg cells is reduced in Treg-specific Cd36-deficient mice with tumor grafts, which is associated with an increased amounts of CD8+ and CD4+FoxP3- tumor-infiltrating lymphocytes (TILs) and reduced tumor growth." (PMID 36568966, 2022). "Several approaches targeting CD163+ pro-tumor macrophages and/or immune suppressive FoxP3+ have been associated with an improved response to immunotherapy and/or chemotherapy and are in pre-clinical or clinical development." (PMID 36551693, 2022). "Our findings further indicated that tumor-specific cellular immunity was downregulated in high-risk individuals compared to low-risk patients and immunohistochemistry analysis found that FOXP3+ Treg was significantly downregulated in LUSC." (PMID 36465363, 2022). "B7-H3 is expressed in NSCLC, and it is associated with tumor progression and metastasis, tumor immune evasion, and infiltrating FOXP3+ Tregs." (PMID 35455052, 2022). "FOXP3 is a X-linked tumor suppressor genes, and heterozygous mutation in FOXP3 has been shown to develop BC in the mice model." (PMID 35879772, 2022).
tumor (continued). "Taken together, CD4+, FOXP3+, PD-L1 TILs and PD-L1 tumor cells possess the potential to predict the recurrence risk of DCIS, and the stromal PD-L1 is more valuable than the others in evaluating DCIS recurrence risk." (PMID 35843951, 2022). "In murine melanoma models, it was discovered that CD4+Foxp3+ T cells migrate to tumor areas through Nrp1 receptor signaling associated with VEGF ligands." (PMID 36203599, 2022). "On the other hand, the expression of ICOS, its association with FOXP3, and its effect on tumour progression are far more complicated." (PMID 35043584, 2022). "The deficiency of IFN production in these tumor-associated DCs is involved in the sustenance of Foxp3+ Tregs’ expansion, in which its increment is in line with the disease stage and provides immunosuppression for tumor cells." (PMID 36009853, 2022). "Paradigmatic driving forces supporting an immunosuppressive tumor microenvironment and typically associated with worse patient prognosis include FOXP3+ regulatory T cells (Tregs), tumor-associated macrophages or myeloid-derived suppressor cells." (PMID 36010856, 2022). "Poor clinical outcomes in many cancers are associated with the invasion of abundant FOXP3+ cells into the tumour tissue; therefore, higher recurrence risk is also expected in the case of higher FOXP3+ expression in CRC." (PMID 36253752, 2022). "CD4+ FoxP3+ Tregs, which exert a suppressive effect on effector T cells implicated in tumor surveillance, have been shown to account for a large proportion of tumor-infiltrating lymphocytes (TILs) in melanoma and breast cancer that do not respond to ICI." (PMID 36678712, 2022). "Several studies have shown that high levels of infiltrated FoxP3+ Tregs in tumor tissues are associated with a better prognosis in CRC patients." (PMID 36146549, 2022). "Most studies dedicated to achieving a better understanding of mechanisms underlying tumor progression and optimizing immunotherapeutic gains have focused on antagonizing Foxp3+CD4+ Tregs." (PMID 35703176, 2022). "The underlying mechanisms of these tumor antigen‐induced CD4+CD69+FOXP3− Tregs in HCC need further investigation for cancer immunotherapy." (PMID 35474948, 2022). "An advanced tumor stage was also positively associated with the number of CD4+ CD25+ FoxP3+ Tregs within the tumor." (PMID 35326519, 2022). "On the other hand, studies report that higher rates of FOXP3+ infiltrating tumor are associated with better patient survival." (PMID 36326418, 2022). "Analysis of the association between OS and CD137+ Treg (CD137+FOXP3+) cell density in the tumor microenvironment revealed that patients with a higher CD137+ Treg density had a worse OS (P=0.0714)." (PMID 35197968, 2022). "In both models, Lm-LLO-CD105A demonstrated an ability to reduce the tumor-associated population of CD4+Foxp3+ Tregs in comparison with either Control Lm or PBS." (PMID 36439126, 2022). "In lung cancer, Foxp3+ Tregs, which suppress auto-reactive T cells to maintain immunological self-tolerance and inhibit autoimmunity, are associated with advanced tumor growth and poor prognosis." (PMID 35874749, 2022). "Their high frequency among CD4+ T cells in tumor-infiltrating lymphocytes or a high ratio of FOXP3+ Treg cells to CD8+ T cells is associated with worse prognosis, especially in patients with breast, gastric, and ovarian cancer." (PMID 35759090, 2022). "Foxp3 levels in the peripheral blood and tumor specimens of cancer patients are associated with tumor progression and poor prognosis." (PMID 36544523, 2022). "As reported, TNFR2 is highly expressed by CD4+Foxp3+ Tregs and is associated with the immunosuppressive activity of tumor-infiltrating Tregs." (PMID 34900985, 2021). "Conversely, the expression of PTEN in tumor cells and a low number of FOXP3+ cells in tumor stroma were both associated with improved OS." (PMID 34362334, 2021).